ITGA5 (integrin subunit alpha 5)
Diseases named in the same sentence as ITGA5 in open-access papers (continued):
Sharing a sentence is not in itself a finding about the gene and the disease.
cancer (continued). "We demonstrate that integrins ITGB1 and ITGA5, which are also upregulated in cancer cells during direct contact with fibroblasts, are involved in YAP1 transcriptional regulation via the CREB pathway." (PMID 36936987, 2023). "Together, these results demonstrate that ZEB1/YAP1 axis in cancer cells potentially functions downstream of ITGA5/ITGB1 interaction with fibronectin on the surface of fibroblasts." (PMID 36936987, 2023). "Here, we found that high expression of FSCN1 and ITGA5 is associated with impaired survival in more than ten cancers, and high expression of TGM2 is also associated with poor prognosis in more than five cancers." (PMID 36978029, 2023). "ITGA5 is a crucial immunotherapy predictive target that is thought to be crucial in the incidence and progression of many cancers." (PMID 36969161, 2023). "Our results however revealed that YAP1 is transcriptionally activated through an ITGA5/ITGB1/CREB pathway after interaction with fibroblasts in cancer cells." (PMID 36936987, 2023). "Recently, the direct interaction was shown to involve integrin-α5β1 (ITGA5/ITGB1) on cancer cells and fibronectin assembled on the surface of CAFs." (PMID 36936987, 2023). "On the other hand, integrin-α5β1 (ITGA5/ITGB1) on cancer cells bind fibronectin assembled on the surface of fibroblasts." (PMID 36936987, 2023). "Some of the results generated in other cancers have demonstrated ITGA5 to exert its effect by modulating PI3K/AKT and MAPK/ERK." (PMID 37430373, 2023). "EFNB2, in line with ITGA5, was highly expressed in cancer tissues, compared with normal tissues, and high expression of EFNB2 conferred a poor prognosis in LSCC patients." (PMID 36438491, 2022). "ITGA5 was known to promote cancer cell migration and invasion through the FAK/STAT3/AKT signaling pathway in TKI-resistant NSCLC." (PMID 36304306, 2022). "Then, the physiopathological impact of ITGA5 in the metabolic programming and cancer immunity cycle progressions was evaluated by GSVA analysis." (PMID 35371978, 2022). "ITGA5 has been shown to potentiate the aggressiveness of cancer cells and their resistance to chemotherapy in animal models." (PMID 35216235, 2022). "It was worth emphasizing that the modulation of ITGA5 of these pathophysiological activities, especially focal adhesion, was highly prevalent across multiple cancers." (PMID 35371978, 2022). "Recently, it has become clear that ITGA5 is essential for cancer proliferation, migration, invasion and metastasis." (PMID 33711961, 2021). "All these studies about the roles of KCNQ1OT1, miR-148a-3p and ITGA5 in various cancers were in line with our present analysis." (PMID 33526991, 2021). "ITGA5 was subsequently identified to interact with the NEAT1/miR-128-3p axis, and NEAT1 safeguarded the cancer-promoting effects of ITGA5 by binding to miR-128-3p competitively." (PMID 34263426, 2021). "Compared to normal tissues, ITGA5 was generally overexpressed in different cancers including multiple types of gastrointestinal tumors." (PMID 33711961, 2021). "Noteworthily, cohesin is reported responsible for EMT/MET via chromatin interactions of mesenchymal genes TGFB1 and ITGA5 loci, implying the significance of conformational changes in cancer metastasis process." (PMID 34689165, 2021). "The expression of mesenchymal markers associated with cancer progression, such as FN1, VTN, and ITGA5, was markedly increased (between 20- and 50-fold)." (PMID 32699630, 2020). "ITGA5 is a member of the family of integrins, which play a role in cell adhesion, proliferation, migration, invasion and cancer metastasis." (PMID 33375067, 2020). "ITGA5 expression was analyzed in a total of 195 HNSCC cancers, including 59 cancers of the oral cavity, 68 of the oropharynx, and 68 of the larynx." (PMID 31661833, 2019). "Recent researches have revealed that over-expression of ITGA5 in cancer cells induced improved invasion ability and epithelial to mesenchymal transition." (PMID 31142737, 2019).
cancer (continued). "Cancer-associated fibroblasts (CAFs) recruit ITGA5high ATCs to form MUs, which further sustain ATC ITGA5 expression by EGF secretion." (PMID 30710055, 2019). "MiR-148b has an antagonistic role with the oncomiR-214 in promoting cancer cell migration in vitro, and in vivo by modulating the expression level of the adhesion molecules integrin alpha 5 (ITGA5), and activated leukocyte cell adhesion molecule (ALCAM)." (PMID 31661891, 2019). "Although ITGA5 is a promising candidate in cancer treatment, its expression pattern and function in neoplastic cells are still elusive." (PMID 25537511, 2015). "To establish the relationship between alcohol, Nm23, ITGA5 and cell invasion, we knocked down ITGA5 with siRNA in T47D cancer cells and measured the ability of alcohol to affect the invasive ability of these cells." (PMID 21838876, 2011). "Additionally, further exploration of the HIF-1α, LOX and ITGA5 axis in various cancer types and its therapeutic targeting will provide deeper insights into its roles in cancer progression and resistance to treatment." (PMID 39857068, 2025). "Quite a few studies have identified both SERPINE1 and ITGA5 as prognostic factors of different types of cancers, indicating these two genes might have synergic effects." (PMID 40458391, 2025). "BASP1, FAP, INHBA, and ITGA5 had been reported to be upregulated in several cancers and could regulate neuronal activity, but their relationship with DKK1, nerves, and HNSCC still remains unknown." (PMID 38525111, 2024). "ITGA5 inhibition suppressed the malignancy of cancer cells and attenuated desmoplasia in CAFs." (PMID 39099892, 2024). "We found that ACTN1 and ITGA5 could interact with other genes to regulate some diseases and this study first explored the interaction between ACTN1 and ITGA5 in the regulation of cancer progression." (PMID 36742137, 2023). "In addition to EC, ITGA5 is over-expressed in numerous carcinoma entities and is an integral part of the pEMT signature of single malignant cells in HNSCC." (PMID 36978029, 2023). "Besides, additional validation of the intimate connection of ITGA5 and immune checkpoints was performed in the pan-cancer set." (PMID 35371978, 2022). "Regardless of the cancer types, genes such as ITGA5, SERPINE1, EIF4EBP1 are majorly associated with bad outcomes; while genes such as ALDH2, DBP, FRAT1, PDCD4 are associated with good outcomes." (PMID 35197510, 2022). "Next, we focused on the prognostic value of ITGA5 in a pan-cancer setting." (PMID 35371978, 2022). "Accumulating studies indicate that the expression of ITGA5 is abnormally elevated in many types of human cancers, which may contribute to cancer cell proliferation and metastasis 29-32." (PMID 36438491, 2022). "ITGA5 is also highly expressed in esophageal squamous carcinoma and head and neck squamous carcinoma, and it also played a role in promoting the proliferation, invasion, and migration of cancer cells." (PMID 36193075, 2022). "Here, public databases were used to determine ITGA5 expression levels in different cancer types." (PMID 33711961, 2021). "In addition, stage I through IV cancer patients with high expression levels of ITGA5 showed worse OS (P < 0.05)." (PMID 33711961, 2021). "ITGA5 has essential roles in tumorigenesis, migration, and invasion in various cancer types." (PMID 34917682, 2021). "In addition, the PrognoScan database was used to investigates the relationship between ITGA5 mRNA levels and the survival of cancer patients using high-throughput analysis and detailed clinical prognosis data." (PMID 33711961, 2021). "From these group of genes, XPC, GSTP1, and ITGA5 were validated on breats cancer samples from TCGA." (PMID 32078659, 2020). "Previous reports showed that the TNF-α could elevate ITGA5 expression via the NF-κB pathway in cancer." (PMID 28629363, 2017). "Notably, MMP14 is ‐ together with AXL, caveolin 1 (CAV1) and ITGA5 ‐ among the top genes contributing to the differentiation of cancer from normal tissue." (PMID 28596300, 2017).
cancer (continued). "For UBC, higher expression of ITGA5 is detected in more malignant tumors." (PMID 27050274, 2016). "ITGA4 and ITGA5 are well-known fibronectin receptors that are altered in many cancer types." (PMID 26056562, 2015). "Transforming growth factor gene (Tgfbi), Spp1 and ITGA5 were up regulated in cancer cells." (PMID 22321936, 2012). "Additionally, results show that suppression of Nm23 by siRNA increases the expression of ITGA5 in the cancer cells, thus, indicating that Nm23 regulates ITGA5 expression." (PMID 21838876, 2011). "Besides, ITGA5 and ITGB1 were risk factors for multiple cancer types." (PMID 36937870, 2023). "In addition, ITGA5 was shown to maintain cancer cell stemness and chemotherapy resistance." (PMID 33711961, 2021). "Moreover, ITGA5 expression correlates with dismal patient outcome in various cancer types." (PMID 30710055, 2019). "Thus, the levels of integrins such as ITGA5 determine how aggressively the cancer cells may spread to secondary tissues." (PMID 21838876, 2011). "Moreover, when ITGA5 was knocked down with siRNA, alcohol was unable to increase the invasion of T47D cancer cells, suggesting that ITGA5 is necessary for alcohol to increase the invasive ability of T47D cancer cells." (PMID 21838876, 2011). "In this study, we designed a cyclic peptide (cyAV3.3) targeting integrin α5 (ITGA5) to disrupt CAF-induced desmoplasia and crosstalk with cancer cells." (PMID 41584360, 2026). "ITGA6 functions as an HPV receptor and has been linked to therapy resistance in HNSCC, making it an especially intriguing target in HNSCC In the cancer genome atlas (TCGA) dataset of HNSCC patients, ITGA3, ITGA5, and ITGA6 all show prognostic resolution." (PMID 40287842, 2025). "Collectively, we propose that COL6A1 and ITGA5 expression in SCC enhances adhesion to the ECM, thereby promoting the malignancy of the cancer." (PMID 40776410, 2025). "Other signature genes, including ITGA5, ANGPT2, and CD44, have recognized roles in cancer progression and are already under investigation as therapeutic targets." (PMID 41374933, 2025). "The upregulation of SPARC, MMP9 and ITGA5 in OSF and OSCC indicates their role in the induction of fibrosis and progression to cancer." (PMID 39865173, 2025). "Considering the clinical impact of ITGA5 and ITGB1 expression on the survival of PDAC patients, we focused our subsequent experiments on this cancer type, for which better treatment options are urgently required due to its poor survival outlook." (PMID 37563605, 2023). "In contrast, for patients with lower number of NART responses, we observed high expression of FN1, ITGA5 and COL3A1, which is correlated with poor survival for cancer patients." (PMID 35410325, 2022). "The results showed that ITGA5, NDST1, CPQ, ITGB1, PIGK, EOGT, and TSPAN4 had amplifications or deletions in most cancers." (PMID 36405728, 2022). "Four proteins (PLAU, ITGA5, ZEB1, and ERBB3) were involved in “microRNAs in cancer” signaling pathway." (PMID 34408977, 2021). "In BC cells, miR-30 inhibition enhances tumorigenesis and metastasis by targeting UBC9 and ITGB3 and osteomimicry of cancer cells by targeting RUNX2, ITGA5 and CDH11." (PMID 33800656, 2021). "Mechanistically, ZNF750 suppresses the expression of some cancer-related genes such as angiogenin, VEGF, RGS5, CD105, ITGA5, ITGB1, and CD44." (PMID 34288812, 2021). "Integrin Subunit Alpha 5 (ITGA5), belongs to the integrin alpha chain family, is vital for promoting cancer cell invasion, metastasis." (PMID 33711961, 2021). "ITGA5 was demonstrated to play a role in TGF-β–mediated activation of PSCs via Smad2 and FAK pathways; and its knockdown inhibited both PSC-induced cancer cell proliferation in vitro and tumor growth in vivo." (PMID 32116785, 2020).
cancer (continued). "For example, re-expression of CNTN1, ITGA5, and CDH23 increased the numbers of colonies in the enhancer KO cells, affecting important properties of cancer cell growth." (PMID 31328168, 2019). "Moreover, our network analysis indicated alterations in MAPK/ERK and Jun-N-terminal kinase pathways and the potential important role of PAX3, VCAN, ARRB2, NR1H2, and ITGA5 that may provide insights into mechanisms involved in longevity and regeneration that are distinct from cancer." (PMID 22477361, 2013). "Meanwhile, other cell-cell adhesion-related molecules, such as laminins (LAMA4, LAMA5, LAMB1, LAMB2 and LAMC2) and integrins (ITGA5, ITGA5, ITGB5, ITGA11 and ITGBL1), are elevated in cancer tissues." (PMID 22905095, 2012). "In addition, ITGA3, ITGA5, and ITGA6 show activating effects on the KEGG pathway in cancer, which is consistent with previous analysis results." (PMID 41602372, 2026). "However, research in this area is still in early stages, targeting MMP9, SPARC and ITGA5 in OSF has the potential to prevent altered ECM remodelling and its contribution to both fibrosis and its progression to cancer." (PMID 39865173, 2025). "Cancer cells interact with fibronectin via integrins: ITGAV, ITGA5, ITGB1 and ITGB3." (PMID 40636307, 2025). "Interestingly, the Carcinoma 3 cluster with high expression of COL6A1 and ITGA5 was predominantly observed in SCC." (PMID 40776410, 2025). "When cases in which ITGA5 was stained in cancer cells (not stromal cells) were considered positive, the expression levels of miR-26a-5p in patients with ITGA5 positivity were significantly lower than those in patients with ITGA5 negativity." (PMID 39288140, 2024). "The receiver operating characteristic (ROC) curve revealed that ITGA5 expression can distinguish patients with cancer from those without cancer [area under the curve (AUC) = 0.944; confidence interval (CI): 0.919 to 0.970]." (PMID 39099892, 2024). "Thus, ITGA5-EVs-148a inactivated CAFs and suppressed the CAF-mediated up-regulation of migration and invasion of cancer cells." (PMID 39099892, 2024). "The expression patterns of 3 key genes were different in the pseudo-trajectories of the 3 types of cells, but IL1B and ITGA5 were more similar, suggesting that CST7 and the other two work in a different mode of action in cancer." (PMID 36969161, 2023). "To test this hypothesis, we depleted ITGA5, ITGB1 and CREB from H69 cancer cells using siRNA duplexes prior to direct co-culture with fibroblasts." (PMID 36936987, 2023). "Expression of other target genes ITGA5 and NOTCH2 could improve the stemness and metastatic potential of hematogenously disseminated cancer cells." (PMID 35008529, 2021). "The signaling pathways involved in ITGA5 were mainly enriched in focal adhesion, ECM-receptor interaction, PI3K-AKT, and cancer-related pathways, mainly involved in protein connection, cell adhesion, focal adhesion, cell matrix receptor interaction, and other biological processes." (PMID 33335550, 2020). "The authors went even one step further and developed a novel ITGA5-antagonizing peptidomimetic (AV3) that could inhibit PSC activation and enhance the cytotoxic effects of gemcitabine in spheroid co-cultures of cancer cell lines with PSCs." (PMID 32116785, 2020). "Integrins, including TGA5, ITGA5, ITGB5, ITGA11, and ITGBL1 elevated in cancer tissues." (PMID 29843204, 2019). "Since IPF and cancer share a lot of common mechanisms, we tested whether IPF tissues and IPF derived fibroblasts expressed higher levels of ITGA5, in comparison to normal tissue samples." (PMID 28629363, 2017). "However, in tumors of the SLURP-1-treated mice, we observed a significant increase in expression of the genes coding α7-nAChR (CHRNA7), pro-oncogenic integrin α5 (ITGA5), and ceramide kinase (CERK), which are responsible for growth and migration of cancer cells." (PMID 37854069, 2023).
cancer (continued). "Furthermore, we found that the membrane proteins CDH2, EGFR, ITGA3, ITGA5, ITGB1, and CALR may have significant effect on cancer prognosis and outcomes, which were further validated in vitro." (PMID 33005184, 2020). "Furthermore, COL4A1 and ITGA5 are not specific to GC, and studying these hub genes can therefore increase the understanding of other cancers." (PMID 30002985, 2018). "Furthermore, we performed in vitro cell staining, which showed induced ITGA5 and FAP expression levels in activated HMFs compared to non-activated HMF or cancer cells." (PMID 36831470, 2023).
infection (9 papers, 2012 to 2025). The state of being infected such as from the introduction of a foreign agent such as serum, vaccine, antigenic substance or organism. "While the airway expression of most SARS‐CoV‐2 entry factors may be lower, it is also interesting to focus on those proteins that remained unchanged between COPD and controls, including Furin, CTSL, ADAM17, and ITGA5, as these factors could still facilitate infection." (PMID 41047996, 2025). "We showed that the expression of ITGA5, p-FAK, p-P85, and p-Akt1 was dramatically decreased following sh-ABHD11-AS1 infection in two CRC cell lines." (PMID 34375304, 2021). "In up-regulated genes of head kidney samples, 2 genes respond to infection by D. pseudospathaceum-clone I (HYAL2, PRF1), 3 to clone XII (RGCC, CYP27B1, CCR9) and 6 to the clone mix treatment (ITGA5, SIX1, ATP1B3, MEF2C, MLF1, MYLPF)." (PMID 25254967, 2014). "Infection also induced the expression of co-stimulatory molecules such CD40, CD83, CD86, adhesion molecules (CD38, Itga5, and ICAM1), and tissue invasion molecules such as MMP12 and MMP14." (PMID 22928052, 2012). "The expression levels of ITGA1, ITGA5, FAK, PIK3R1, PIK3CA and AKT1 were significantly higher in the 1 MOI L. salivarius-treated group, than in untreated cells at 2, 8, and 16 h post-PEDV infection." (PMID 34957282, 2021).
gastrointestinal tumors (6 papers, 2021 to 2025). "Also, ITGA5 expression measured by immunohistochemistry in gastrointestinal tumor samples was proved to be associated with gene expression signatures related to immunotolerant populations, such as TAMs, Th2 cells and protumoral M2-like cells." (PMID 37284199, 2023). "Because of its correlation with immune infiltration, ITGA5 is also a prognostic gene for gastrointestinal tumors." (PMID 35954323, 2022). "Our results indicated that ITGA5 expression was significantly and negatively correlated with immune purity in four types of gastrointestinal tumors, including COAD, ECAD, STAD and READ." (PMID 33711961, 2021). "ITGA5 was generally overexpressed and correlated with worse prognosis in multiple types of gastrointestinal tumors." (PMID 33711961, 2021). "Here, we explored the expression level, prognostic value, protein interaction network and enrichment analysis of ITGA5 in gastrointestinal tumors." (PMID 33711961, 2021). "Interestingly, we also found that ITGA5 also has a significant impact on the prognosis of patients in some non-gastrointestinal tumors." (PMID 33711961, 2021). "Therefore, to better understand the role of ITGA5 in gastrointestinal tumors, the relationship between ITGA5 expression and immune infiltration in gastrointestinal tumors was investigated using the TIMER database." (PMID 33711961, 2021). "However, the correlation between ITGA5 expression and immune infiltration in gastrointestinal tumors remain unclear." (PMID 33711961, 2021).